APOL1 (apolipoprotein L1)
Diseases named in the same sentence as APOL1 in open-access papers (continued):
Sharing a sentence is not in itself a finding about the gene and the disease.
kidney disease (continued). "This indicates that along with social and clinical risk determinants, genetic background contributes to the APOL1 HR kidney disease relationship." (PMID 37962879, 2024). "Even though APOL1 is thought to be dispensable, its risk alleles have been proved to worsen kidney disease via cytotoxic effect on podocytes, furthermore, according to our research, APOL1 has a critical role in ccRCC." (PMID 38680858, 2024). "Overall, our findings are in line with previous studies carried out in yeast, cultured human podocytes, APOL1 transgenic mice and the age-related changes observed in patients with APOL1-associated kidney diseases." (PMID 37969018, 2023). "People of African ancestry who carry the APOL1 risk alleles G1 or G2 are at high risk of developing kidney diseases through not fully understood mechanisms that impair the function of podocytes." (PMID 37969018, 2023). "In summary, here we present results from the largest GWAS on DME to date which highlights APOL1, a gene canonically associated with kidney disease, and broadens its impact to a second diabetic complication." (PMID 37585454, 2023). "The APOL1 G1 risk allele made mice more susceptible to kidney disease in a lipotoxicity-driven FSGS model." (PMID 37509442, 2023). "This is especially important at the APOL1 locus, for which multiple alleles in APOL1 have strong associations to risk of kidney disease in individuals of African descent." (PMID 37585454, 2023). "These newly generated fly models for APOL1-dependent risk for susceptibility to renal disease were used in all assays described in this manuscript." (PMID 37969018, 2023). "Overall, ∼13% of African Americans carry the APOL1 high-risk genotype (two risk alleles) that confers a 3–30-fold increased risk of developing different types of kidney disease." (PMID 37969018, 2023). "Specifically, the APOL1 gene and its genetic variants have been shown to have a strong association with renal disease." (PMID 37485073, 2023). "Nonetheless, it remains to be determined how these changes mimic those induced by APOL1 risk alleles in patients with APOL1-associated kidney diseases." (PMID 37969018, 2023). "Including the genotype for rs73885319 (variant at the APOL1 locus)—another highly differentiated allele that explains much of the difference in risk of kidney disease between individuals of African and European ancestry—also did not change hg2." (PMID 37255673, 2023). "Such as the case of genetic susceptibility to kidney disease, particularly for variants in the APOL1 gene that are associated with kidney disease." (PMID 37600748, 2023). "Overall, this new pathologic paradigm supports the assumption that the risk of developing APOL1-associated kidney diseases is a function of the APOL1 expression levels in podocytes; and follows a recessive gain-of-function mode of inheritance." (PMID 37925499, 2023). "Another example, where Drosophila has helped to gain some insights into human disease, is apolipoprotein-L1 (APOL1) associated kidney disease." (PMID 37171583, 2023). "Genetic modifiers have been suggested but, to date, the identification of modifier genetic variants for APOL1-mediated kidney disease and, particularly, FSGS, remains elusive." (PMID 38036523, 2023). "APOL1 has been widely studied for its expression and variants with many diseases, especially with kidney diseases." (PMID 38017264, 2023). "The locus on Chromosome 22 is tagged by a functional variant in the gene APOL1, a gene previously associated with kidney disease in African descent populations, suggesting APOL1 plays a broader role in diabetic complications than previously thought." (PMID 37585454, 2023). "Given the growing importance of APOL1 polymorphism in defining the prognosis of kidney diseases, estimating the frequency of G1 and G2 alleles in populations of African descent is of paramount concern." (PMID 36217118, 2022).
kidney disease (continued). "In 18 instances, the racial or ethnic differences in risk were attributed to genetic causes (e.g., APOL1 associations with kidney disease in Black patients, associations between sickle cell trait and sub-Saharan African ancestry)." (PMID 33987787, 2022). "Apolipoprotein L1 (APOL1) gene variants G1 and G2 are associated with kidney disease among HIV infected individuals of African descent in the USA as well as among black population in South Africa." (PMID 36227935, 2022). "Collapsing glomerulopathy is the most fulminant pattern of injury associated with APOL1-nephropathy." (PMID 35281116, 2022). "To further understand the specific contribution of the G1 and G2 APOL1 risk variants in kidney disease, we generated isogenic RCC clones expressing these variants." (PMID 35159001, 2022). "Several studies have however shown that the presence of high-risk APOL1 alleles alone was associated with minimal risk for the development of APLO1 induced kidney disease among individuals of recent African ancestry." (PMID 36034035, 2022). "In vitro assays revealed that only APOL1 variants that were associated with kidney disease were able to lyse and provide resistance to the protozoan Trypanosoma brucei rhodesiense, which causes sleeping sickness in humans and primates." (PMID 36588788, 2022). "The survival advantage of African Americans is associated with the presence of APOL-1 genetic variants even though the APOL-1 genetic variant is linked to greater incidence of kidney disease in this group." (PMID 35950159, 2022). "Coprimary outcomes were the change in 3-month systolic blood pressure and 12-month urine kidney disease screening comparing intervention patients with high-risk APOL1 genotypes and those with low-risk APOL1 genotypes." (PMID 35244702, 2022). "Mechanisms of increased kidney disease risk and cell injury, causally associated with these APOL1 gene variants, have been extensively studied." (PMID 35159001, 2022). "APOL1 risk variants G1 and G2 are known to result in risk for kidney disease in patients of African ancestry and associate with a heterogeneous pattern of injury." (PMID 35281116, 2022). "Susceptibility to different kinds of renal diseases is largely increased by APOL1 risk variants, with the highest risk for HIV nephropathy (odds ratio, [OR] 29–89), FSGS (OR 17), and hypertensive nephropathy (OR 7–11)." (PMID 35207681, 2022). "Recent studies have shown a positive correlation between MYH9 and APOL1 polymorphisms and kidney disease." (PMID 35386255, 2022). "APOL1 high-risk genotypes were strongly associated with kidney disease in people of African ancestry with HIV and accounted for approximately half of ESKD cases in this cohort." (PMID 35497797, 2022). "Previous studies have investigated the role of various single nucleotide polymorphisms (SNPs) and the APOL1 risk variants in kidney diseases." (PMID 36250097, 2022). "APOL1 G1 and G2 RV contribute to increased risk for kidney disease in black populations, although the disease mechanism has still not been fully deciphered." (PMID 35159001, 2022). "We conducted a cross-sectional study investigating the association between APOL1 renal risk alleles and kidney disease in people of African ancestry with HIV in the UK." (PMID 35497797, 2022). "Two alleles (G1 and G2) of the apolipoprotein 1 gene (APOL1) predispose people of African descent to developing or accelerating the course of certain types of kidney disease." (PMID 36217118, 2022). "Transgenic mice that express wild-type or risk variant APOL1 from an albumin promoter were treated to cause kidney injury and evaluated for renal disease and pathology." (PMID 36279295, 2022). "This study showed a high population frequency of the individual risk alleles of the APOL1 gene with higher frequencies noted among HIV positive patients with kidney disease." (PMID 36227935, 2022).
kidney disease (continued). "A decade after the evidence that genetic variants in APOL1 are associated with kidney disease, much remains to be understood about the genetics and evolutionary aspects of this discovery." (PMID 36588788, 2022). "The factors associated with onset and progression of kidney disease in individuals with well-controlled HIV who have APOL1 high-risk genotypes require further study." (PMID 35497797, 2022). "Of these genes, APOL1 (apolipoprotein-L1) has been observed significantly associated with kidney disease, especially in terms of HIV-related chronic renal disease." (PMID 35250881, 2022). "Multivariable logistic regression was used to estimate the associations between APOL1 high-risk genotypes (G1/G1, G1/G2, G2/G2) and kidney disease outcomes." (PMID 35497797, 2022). "Up to 12-13% of African Americans have the two renal risk variants of the APOL1 gene that predispose to kidney disease." (PMID 36034035, 2022). "Despite the increased risk of kidney disease, the frequency of APOL1 risk variants in people of African ancestry is high." (PMID 35207681, 2022). "The strongest associations have been reported for HIV-associated nephropathy, with odds ratio (OR) 29 in African Americans and OR 89 in South Africans3,5, suggesting a strong interaction between APOL1 and HIV." (PMID 33674766, 2021). "Pathogenic gain-of-function mutations typically show a dominant inheritance pattern, while the kidney disease phenotype associated with ApoL1 variants is recessive." (PMID 33380423, 2021). "Further, although APOL1 variants are postulated to increase susceptibility to kidney disease by effects on podocytes and their cytoskeleton, the exact mechanism through which they cause kidney disease is not proven." (PMID 33822824, 2021). "These include the H3Africa Kidney Research Network which is looking at the APOL1 polymorphisms in kidney disease." (PMID 34671490, 2021). "Humans with two copies of APOL1 renal risk variants G1 (dbSNP: rs73885319 and rs60910145) and G2 (rs71785313) have a higher risk of developing kidney disease than those with the APOL1 G0 allele (GenBank: EAW60091.1 and AAI12944.2)." (PMID 34331942, 2021). "Using similar methods, we compared the lipid vesicle binding properties of the reference version of ApoL1 with the kidney-disease-associated variants under conditions supporting optimal Cl or K permease activities." (PMID 33380423, 2021). "This was supported by the association of APOL1 renal risk variants with kidney disease triggered by interferon therapy, and more recently COVID-19 infection." (PMID 34331942, 2021). "About 13% of African Americans have the APOL1 high-risk genotype, and these individuals have a 3- to 30-fold increased risk of various forms of kidney disease." (PMID 35145920, 2021). "Two variants of the APOL1 gene, named G1 and G2, have been associated with an increased risk of developing renal disease in individuals of African ancestry." (PMID 33807271, 2021). "We here present results of studies of ion permease activities of ApoL1 and its kidney-disease-associated variants that yielded several significant results." (PMID 33380423, 2021). "If and how APOL1 risk variants are associated with kidney diseases through altered lipid metabolism remains to be established." (PMID 34442464, 2021). "APOL1 genetic variants are an important cause of kidney disease, affecting individuals who have sub-Saharan African ancestry." (PMID 34765626, 2021). "Infection with HIV is believed to be the strongest known risk factor for APOL1-associated kidney disease as the innate immune response to HIV upregulates APOL1 gene expression." (PMID 35095882, 2021). "The top SNP was in linkage disequilibrium with two known APOL1 kidney disease risk variants (G1 r2 = 0.47 and G2 r2 = 0.12 based on the African populations of the 1000 Genomes Project)." (PMID 33850243, 2021).
kidney disease (continued). "We performed various cell biological assays and assessed podocyte specific functions to validate our cell lines as a model to study mechanisms of APOL1-associated kidney disease." (PMID 34440683, 2021). "Inheriting two copies of the APOL1 risk variants (RVs), termed G1 and G2, have been reported to significantly increase the risk of various kidney diseases." (PMID 34440683, 2021). "Participants in this study had CKD and were genotyped on the Illumina Infinium MegaEX mainly for their APOL1 status and other genome-wide variants possibly associated with kidney disease and related conditions." (PMID 31797629, 2020). "Recently evolved alleles of Apolipoprotein L-1 (APOL1) provide increased protection against African trypanosome parasites while also significantly increasing the risk of developing kidney disease in humans." (PMID 32427098, 2020). "In summary, our results demonstrate that the kidney disease associated variants of APOL1 form cytotoxic cation channels at the cell surface." (PMID 32427098, 2020). "The discovery of kidney disease risk variants in the APOL1 gene that are found predominantly in individuals with African ancestry demonstrated this potential." (PMID 32140257, 2020). "African Americans are at increased risk of kidney diseases due to the high prevalence of G1 and G2 as risk alleles of the APOL1 gene." (PMID 32892322, 2020). "The goal of this study was to investigate the underlying mechanisms driving APOL1-mediated kidney disease." (PMID 32427098, 2020). "Permeability transition pore opening is facilitated in the presence of variants of Apolipoprotein L1 (APOL1) associated with kidney disease and linked to mitochondrial dysfunction." (PMID 33585458, 2020). "In this regard, an in vivo study has shown that transgenic expression of human APOL1 risk variants in podocytes induces kidney disease in mice." (PMID 32106480, 2020). "Allelic variants in the gene for apolipoprotein LI, APOL1, are found only in populations of African ancestry, and have been shown to contribute significant risk for kidney disease." (PMID 32434471, 2020). "As the APOL1 effect is largely recessive, the ~ 25% of the West African population carrying APOL1 HR genotypes are at substantially increased risk of kidney disease." (PMID 31182139, 2019). "Due to the low frequency of the G1 and G2 risk alleles in South African populations, our study was underpowered to examine the role of APOL1 risk alleles in the progression of kidney disease." (PMID 31754646, 2019). "Variants of the APOL1 gene found in AAs are associated with a higher rate of kidney disease and play a complex role in cardiovascular disease." (PMID 31532792, 2019). "The mechanisms by which the APOL1 gene contributes to renal disease risk and potential cardiovascular outcomes are questions that currently remain largely unanswered." (PMID 31532792, 2019). "APOL1 is expressed in renal cells, however, the pathogenic events that lead to renal cell damage and kidney disease are not fully understood." (PMID 31661509, 2019). "On the other hand, a recessive inheritance mode for kidney disease risk in association with the APOL1 risk alleles in genetic epidemiologic studies is more consistent with a loss rather than a gain of function by APOL1 risk alleles." (PMID 30837512, 2019). "On the other hand, incomplete penetrance of the APOL1 risk alleles in APOL1-associated kidney disease implicates environmental factors as major contributors to APOL1 expression and kidney injury in African Americans18." (PMID 31664093, 2019). "The association between two variant alleles in the APOL1 gene found primarily in individuals of sub-Saharan ancestry and a number of kidney diseases has been reported." (PMID 31532792, 2019). "Examples include the human immunodeficiency virus- (HIV-) associated nephropathy, lupus nephritis, sickle cell nephropathy, focal global glomerulosclerosis, and rapid failure of transplanted kidneys from donors with APOL1 high-risk variants." (PMID 31929905, 2019).
kidney disease (continued). "One such gene is Apo-lipoprotein-L1 (APOL1) whose variants G1 and G2 are associated with kidney disease in African Americans and have been predicted to have been selected because they provide protection against HAT." (PMID 31412021, 2019). "APOL1 risk alleles G1 or G2 are associated with a kidney disease phenotype exclusively in people of recent African ancestry." (PMID 29880816, 2018). "A common genetic predisposition to kidney disease in African Americans and the sub-Saharan African blacks is the possession of apolipoprotein L1 (APOL1)." (PMID 29903699, 2018). "It will also highlight if the risk of acquiring RPS is dependent on having APOL1 kidney disease risk variants among the children with confirmed febrile UTI." (PMID 29903699, 2018). "It would therefore be of great interest if larger population studies are conducted to ascertain the kidney disease-APOL1 association across African population groups." (PMID 30340464, 2018). "Several of these second hits have been identified, including exogenous interferon administration, lupus nephritis, and sickle cell disease, but HIV is the most potent “second hit” to promote kidney disease in persons with high risk APOL1 genotypes." (PMID 29930940, 2018). "Certain variants in APOL1, a gene located on Chromosome 22 that encodes apolipoprotein L1 (APOL1), are associated with the progression of many kidney diseases." (PMID 30557319, 2018). "We report that APOL1 genetic variants that are strongly associated with kidney disease among African descent individuals activate PKR and this contributes to podocyte injury in vitro and in vivo." (PMID 30417125, 2018). "APOL1 gene polymorphisms have also been more intensely associated with the risk of kidney disease previously attributed to MYH9." (PMID 29862302, 2018). "The genetic basis of this disparity was elucidated in a seminal study in 2010 in which the authors reported that variants of the APOL1 gene, which encodes the Apolipoprotein L1 (ApoL1) protein, are strongly associated with risk of kidney disease." (PMID 29930940, 2018). "It has been suggested that the G1 and G2 alleles of APOL1 which increase the risk of developing kidney disease are under selection because they confer resistance to HAT." (PMID 29077717, 2017). "Here, we report the first association study between APOL1 G1 and G2 kidney disease risk variants and T.b." (PMID 28537557, 2017). "Apolipoprotein L1 (APOL1) has two sets of sequence variants that are risk factors for kidney disease development, APOL1G1 (substitution mutation) and APOL1G2 (deletion mutation)." (PMID 28385815, 2017). "Results indicated that the apoL1 proteins encoded by only kidney disease-associated variants possess the ability to lyse T. brucei rhodesiens." (PMID 28842513, 2017). "In populations of African ancestry, two apolipoprotein-L1 (APOL1) variants with a recessive kidney disease risk, named G1 and G2, occur at high frequency." (PMID 28537557, 2017). "It would be helpful for the future study which concerned the associations between APOL1 gene variations and kidney diseases." (PMID 28800731, 2017). "Variant APOL1 is cytotoxic to multiple cell types, potentially contributing to its association with increased risk of renal disease and CVD." (PMID 28850570, 2017). "APOL1 rs73885319 is also known as the G1 allele of APOL1 and is associated with kidney disease in African Americans and the relatively high frequency of this deleterious allele was assumed to be due to selection by HAT." (PMID 29059176, 2017). "The two variants (G1: rs73885319 A > G, and rs60910145 T > G; G2: rs71785313 TTATAA/−) of APOL1 has been shown to be associated with an increased susceptibility of multiple kinds of kidney diseases, particularly in African Americans." (PMID 28800731, 2017). "In contrast to renal disease, APOL1 polymorphisms have been inconsistently correlated with cardiovascular risk." (PMID 28850570, 2017).